STAG3L5P (STAG3 cohesin complex component like 5, pseudogene)
Gene: Transcribed unprocessed pseudogene on chromosome 7 (100,338,197 to 100,338,886, forward strand). Ensembl gene ENSG00000242294.
Diseases named in the same sentence as STAG3L5P in open-access papers:
STAG3L5P is named in the same sentence as 4 diseases in open-access papers, as found by Europe PMC text mining. Sharing a sentence is not in itself a finding about the gene and the disease. The quoted sentences say what the papers report.
bladder cancer (2 papers, 2023 to 2025). "STAG3L5P-PVRIG2P-PILRB is up-regulated in bladder cancer and has been identified as a prognostic necroptosis-related lncRNA." (PMID 41303378, 2025). "STAG3L5P‐PVRIG2P‐PILRB and other lncRNAs comprise a prognostic signature for survival of patients of bladder cancer." (PMID 36237132, 2023).
renal papillary cell carcinoma (1 paper, 2022). "The potential lncRNA of hsa-let-7d-5p and hsa-let-7e-5p/P2RX1 axis was STAG3L5P-PVRIG2P-PILRB, which has been reported to be up-regulated in renal papillary cell carcinoma and may be associated with poor prognosis." (PMID 35585027, 2022).
tumor (3 papers, 2022 to 2025). "These lncRNAs, LINC02428, STAG3L5P-PVRIG2P-PVRIG2P-PILRB, NSMCE1-DT, MYOSLID, MRPS9-AS1, NCBP2-AS1, WARS2-AS1, and LENG8-AS1, were found to be upregulated in tumor tissues." (PMID 40149492, 2025). "While other lncRNAs AC021321.1, STAG3L5P-PVRIG2P-PILRB, AC068196.1 and AC104825.1 in our signature have not been reported in any published tumor studies, all were studied for the first time in our study." (PMID 35571063, 2022).
STAG3L5P also shares sentences with these, for which no sentence is quoted: colorectal cancer (1 paper).